UCP1 (uncoupling protein 1)
Diseases named in the same sentence as UCP1 in open-access papers (continued):
Sharing a sentence is not in itself a finding about the gene and the disease.
diabetic retinopathy (4 papers, 2013 to 2021). "After stratification of patients according to the presence/absence of vascular complications, we found significant associations of variants in the CAT, FTO, and UCP1 genes with diabetic retinopathy and nephropathy." (PMID 29410390, 2018).
Fever (4 papers, 2018 to 2024). Body temperature elevated above the normal range. "In order to investigate the thermoeffectors involved in CLP-induced fever, we first accessed the content of UCP1 protein in the iBAT of septic rats as an approach to indirectly evaluate the participation of non-shivering thermogenesis in this process." (PMID 39522078, 2024). "This is consistent with prior observations that UCP-1-dependent thermogenesis is dispensable for IL-1β- and LPS-induced fever." (PMID 29746591, 2018). "The increased UCP1 amount had minimal effects on thyroxine-induced thermogenesis and pyrexia." (PMID 31151797, 2019). "We found that LPS treatment could significantly increase the rectal temperature and dorsal interscapular surface temperature (contribute to fever) of mice, and the mRNA levels of TNFα, IL-6, Ucp1, and Pgc1α in the BAT, but did not affect the expression of Cpt1α and Cidea." (PMID 36430282, 2022). "Also the increase in body temperature was UCP1-independent; this elevated body temperature was thus not hyperthermia but was due to a thyroid hormone-induced increase in the defended body temperature: pyrexia." (PMID 31151797, 2019).
ovarian carcinoma (4 papers, 2011 to 2025). A malignant neoplasm originating from the surface ovarian epithelium. "The PRAT ‘browning’ process has also been associated with poor prognosis in ovarian cancer, UCP1 overexpression in perirenal fat being considered as a promoter of ovarian cancer cell progression." (PMID 40227577, 2025). "In summary, increased UCP1 expression is associated with better prognosis and increased levels of immune infiltration in ovarian cancer." (PMID 35090503, 2022). "These interesting observations should be further investigated to understand the causal factors of UCP1 up‐regulation in adipose tissue and metabolic dysregulation in ovarian cancer." (PMID 35044098, 2022). "The results revealed that the increased UCP1 mRNA was significantly associated with improved overall survival of Stage 3 and Grade 3 ovarian cancer patients (p < 0.05)." (PMID 35090503, 2022). "The survival analysis revealed that highly expressed UCP1, UCP2, UCP3 and UCP5 were associated with longer OS, PPS and PFS in patients with ovarian cancer." (PMID 35090503, 2022). "CancerSEA analysis indicated possible functions of UCPs in OV cells and the results hinted that UCP1 mainly participates in tumor progression by regulating the malignant behavior of ovarian cancer cells, including invasion, EMT, metastasis." (PMID 35090503, 2022). "Log rank test analyses showed a significant association between the elevated UCP1 mRNA levels and improved OS, post-progression survival (PPS), and progression-free survival (PFS) (p < 0.05) of all ovarian cancer patients." (PMID 35090503, 2022). "Therefore, we showed that UCP1 may play an indispensable relevant role in immune cell infiltration levels by regulating oncogenes, and may serve as a potential prognostic biomarker for ovarian cancer." (PMID 35090503, 2022).
cardiomyopathy (3 papers, 2018 to 2022). A disease of the heart muscle or myocardium proper. "BAT transplantation isolated from wild-type mice recovers catecholamine-induced cardiomyopathy, which leads to fibrosis in Ucp-1-/- mice." (PMID 33922704, 2021). "In EAT, increased HO-1 expression depends on the PGC-1α–UCP-1 axis, which subsequently decreases free radical and ROS production, thus reducing cardiomyopathy." (PMID 30400212, 2018).
clear cell renal cell carcinoma (3 papers, 2021 to 2022). "PLCL1 was demonstrated to induce abnormal lipid metabolism in tumor cells by interacting with metabolism-related gene uncoupling protein 1 (UCP1), thereby repressing progression of clear cell renal cell carcinoma (ccRCC)." (PMID 36389725, 2022). "In this context, an increased UCP-1 expression of PRAT is considered a negative prognostic factor in patients with clear cell renal carcinoma." (PMID 33800984, 2021).
colorectal cancer (3 papers, 2022 to 2026). A primary or metastatic malignant neoplasm that affects the colon or rectum. "A study performed in mice with colorectal cancer cachexia revealed that key regulators of lipid accumulation and fatty acid β-oxidation were upregulated, including expression of UCP1, suggesting active BAT." (PMID 36670439, 2023). "In fact, we found that Ucp1 mRNA levels were lower in colorectal and pancreatic cancer patients vs. controls, and the UCP1 protein level was higher in pancreatic cancer patients vs. controls and vs. colorectal cancer patients." (PMID 35454855, 2022). "We observed the lower expression of Ucp1 in pancreatic and colorectal cancer vs. controls." (PMID 35454855, 2022).
endothelial dysfunction (3 papers, 2021 to 2023). In vascular diseases, endothelial dysfunction is a systemic pathological state of the endothelium (the inner lining of blood vessels) and can be broadly defined as an imbalance between vasodilating and vasoconstricting substances produced by (or acting on) the endothelium. "We also carried out ex vivo studies demonstrating that UCP1 in PVAT confers direct protection against endothelial dysfunction in intact aortic rings from mouse and pig models." (PMID 34878840, 2021). "Notably, the difference in vasodilatation among WT pigs and UCP1 KI pigs with DMHC became indistinguishable when PVAT was removed from LAD, supporting the notion that UCP1 alleviates DMHC-induced endothelial dysfunction through its action on PVAT." (PMID 34878840, 2021).
Hypercholesterolemia (3 papers, 2013 to 2021). An increased concentration of cholesterol in the blood. "Although the detailed molecular link between UCP1 expression and hypercholesterolemia is not known at this time, activation of the sympathetic nervous system is essentially required for the cold-induced hypercholesterolemia and atherosclerotic plaque development." (PMID 23823482, 2013).
hyperthyroidism (3 papers, 2018 to 2022). Overactivity of the thyroid gland resulting in overproduction of thyroid hormone and increased metabolic rate. "T3 can directly activate UCP1, even without a sympathetic stimulus, and hyperthyroidism has been demonstrated to increase BAT activity in humans." (PMID 30724123, 2019).
Mitochondrial myopathy (3 papers, 2013 to 2021). "Muscle-specific UCP1 expression in mice resulted in mitochondrial myopathy, with structurally abnormal mitochondria found only in the transgenic line of mice with higher expression levels of UCP1." (PMID 24386355, 2013).
Nephropathy (3 papers, 2018 to 2022). A nonspecific term referring to disease or damage of the kidneys. "An analysis of 40 single-nucleotide polymorphisms (SNPs) in 40 genes of 503 T2DM patients vs. 580 healthy controls on a Sequenom platform identified SNPs in the CAT, FTO and UCP1 genes associated with the retinopathy and nephropathy complications of T2DM." (PMID 36013384, 2022). "Therefore, we speculated that Danhong injection reduces kidney damage in diabetic rats partially through the energy metabolism regulation mediated by PPARγ/UCP-1 signaling pathway." (PMID 29849705, 2018).
nonalcoholic fatty liver disease (3 papers, 2022 to 2024). "Here, decreased UCP1 in NK cells was identified in patients with advanced nonalcoholic fatty liver disease." (PMID 39033153, 2024).
pancreatic cancer (3 papers, 2022). "We documented higher UCP1 protein levels in pancreatic cancer patients vs. colorectal (p = 0.002) and vs. controls (p = 0.031)." (PMID 35454855, 2022). "Different markers of the browning of SAT are modulated, and pancreatic cancer showed changes in UCP1 and PGC1α; PGC1α was highly expressed in cachectic patients, with clinical implications that should be further clarified." (PMID 35454855, 2022). "On the other hand, UCP1 protein levels were increased in pancreatic cancer patients, suggesting potential translational regulation according to the different cancer type." (PMID 35454855, 2022). "We observed that the modulation of different markers of the browning of SAT in gastrointestinal cancer and, in particular, pancreatic cancer showed significant changes in UCP1 and PGC1α; PGC1α was highly expressed in cachectic patients." (PMID 35454855, 2022). "In conclusion, we found that in patients with gastrointestinal cancer, different markers of browning are modulated and, in particular, pancreatic cancer showed significant changes in terms of UCP1 and PGC1α." (PMID 35454855, 2022). "We observed that the levels of UCP1 expression and p38 phosphorylation in iWAT (p < 0.01, p < 0.001) and vWAT (p < 0.001, p < 0.001) of mice with pancreatic cancer were significantly increased, compared to those obtained from the control animals." (PMID 35893867, 2022). "Since UCP1 and p38 phosphorylation are key components of the p38 MAPK pathway and were found to be elevated in the WAT of mice with pancreatic cancer in this study, we further tested whether p38 MAPK inhibitors may block the browning of white adipocytes and slow CAC." (PMID 35893867, 2022).
Stroke (3 papers, 2011 to 2021). Sudden impairment of blood flow to a part of the brain due to occlusion or rupture of an artery to the brain. "In this study, we elucidated the association of three polymorphisms located in the UCP-1 promoter and coding region with DP among Korean stroke patients." (PMID 23043591, 2012). "We showed an association of UCP1 polymorphisms with DP in Korean stroke patients." (PMID 23043591, 2012). "In this study, we investigated the genetic distribution of the 3 SNPs of UCP-1 among Korean stroke patients with cerebral infarction (CI) DP or non-DP group and compared with normal group." (PMID 23043591, 2012).
adrenal neoplasm (2 papers, 2019 to 2022). "They assessed in the perirenal region of PPGL higher expression of UCP1, CIDEA, ELOVL3, EBF3, FBXO31 and LHX8, but not TNFSRF9, TBX1 or TMEM26, in comparison with seven subjects with non-functional adrenal tumors." (PMID 35327387, 2022).
Anorexia (2 papers, 2019 to 2021). Lack of desire to eat (loss of appetite). "When calculating overall energy balance, this loss of GDF15-dependent day time anorexia together with a preserved elevated night time energy intake proved sufficient to explain the progressive fat accumulation that we observed in Gdf15 ablated UCP1-tg mice." (PMID 33464381, 2021). "Intriguingly, the day time restricted GDF15 induced anorexia leads to a “voluntary” time restricted feeding in the UCP1-tg mouse model." (PMID 33464381, 2021). "Moreover, recent data demonstrated that mitochondrial stress-induced GDF15 promotes a day-time restricted anorexia and systemic metabolic remodeling as shown in UCP1-transgenic mice, where both FGF21 and GDF15 are induced as myomitokines." (PMID 33464381, 2021).
Anxiety (2 papers, 2019 to 2022). Intense feelings of nervousness, tension, or panic often arise in response to interpersonal stresses. "Male and female constitutive UCP-1 knock-out (KO) mice were used to investigate the consequences of UCP-1 deficiency on anxiety-related and depression-related behaviors under mild thermogenic (23°C) and thermoneutral (29°C) conditions." (PMID 36194650, 2022). "Using the heightened anxiety response of UCP-1 KO mice in the contextual fear paradigm as a proxy of their emotional phenotype allows integration of the observed effects across models and paradigms in the present study." (PMID 36194650, 2022). "UCP-1 KO mice displayed a selective enhancement of anxiety-related behavior exclusively under thermogenic conditions, but not at thermoneutrality." (PMID 36194650, 2022). "Female and male UCP-1 KO mice presented with enhanced innate anxiety-like behavior in the LD-BOX, the NSF, and the EPM." (PMID 36194650, 2022). "We provide evidence for a novel role of UCP-1 in the regulation of emotions that manifests as inhibitory constraint on anxiety-related behavior, exclusively under thermogenic conditions." (PMID 36194650, 2022). "Thus, it can be hypothesized that UCP-1 may constitute a hitherto unknown molecular mediator of the innate defense network to contribute to the control of anxiety-like behavior." (PMID 36194650, 2022). "Together these observations indicate that a derangement of either the neural or the humoral stress response system is unlikely to account for the increase in anxiety-like behavior in UCP-1 KO mice." (PMID 36194650, 2022). "SIGNIFICANCE STATEMENT In this first description of a temperature-dependent phenotype of emotional behavior, we propose uncoupling protein-1 (UCP-1), the key component of the thermogenic function of the brown adipose tissue, as molecular break controlling anxiety-related behavior in mice." (PMID 36194650, 2022). "In addition, UCN3/CRHR2 possesses a variety of biological effects in the regulation of stress and anxiety, as well as stimulating sympathetic outflow, which was characterized by increased thermogenesis of BAT and upregulated Ucp1 in BAT." (PMID 31379744, 2019). "However, increasing systemic FGF-21 levels in WT mice did not phenocopy augmented anxiety-like behavior observed in UCP-1 KO mice, and blocking FGF-21 activity in KO mice did not rescue their phenotype." (PMID 36194650, 2022). "Thus, we observe a temperature-dependent regulation of anxiety-like behavior by UCP-1, which is not contingent on BAT." (PMID 36194650, 2022). "Together, our results show that the increase in anxiety observed in UCP-1 KO mice is not induced by enhanced levels of FGF-21 or other direct humoral or neural communicatory signals from BAT to brain, proposing a role for brain-expressed UCP-1 in the regulation of emotional behavior." (PMID 36194650, 2022).
cardiac hypertrophy (2 papers, 2022 to 2025). "PPAR-γ and UCP1 are also the target genes of miR-27b-3p.15,17 Both PPAR-γ and UCP1 play antagonistic roles in cardiac hypertrophy." (PMID 34358309, 2022).
colon adenocarcinoma (2 papers, 2012 to 2022). "Ras oncoproteins also directly increase the expression of uncoupling protein (UCP)-1, and UCP-2 expression has been found to be increased in most human colon adenocarcinomas in which up to 60% contain K-Ras mutations." (PMID 22917272, 2012).
diabetic nephropathy (2 papers, 2018). "This notion is further bolstered by the finding that two other SNPs (rs1800592 and rs3811787) in the promoter region of UCP1 gene are implicated in diabetic nephropathy risk." (PMID 29410390, 2018). "The LPD prevented the progression of diabetic status; this effect may have been associated with the reduction of FW and the elevation of plasma FGF21 and HMW adiponectin, as well as UCP1 expression in BAT, resulting in suppression of diabetic nephropathy." (PMID 29507597, 2018).
endometrial carcinoma (2 papers, 2016 to 2022). A malignant tumor arising from the epithelium that lines the cavity of the uterine body. "Indeed, we managed to find a positive correlation between UCP1 expression on protein as well as mRNA level in omental fat and endometrial cancer clinical stage." (PMID 27853670, 2016).
gastric cancer (2 papers, 2021 to 2022). A primary or metastatic malignant neoplasm involving the stomach. "Exosomes from gastric cancer (GC) cells deliver ciRS-133 to adipocytes, which inhibits the expression of miR-133 and activates the expression of PRDM16 and UCP1, thereby accelerating the metabolic rate of mature adipocytes, increasing oxygen consumption and heat production." (PMID 33912560, 2021).
Genetic obesity (2 papers, 2020 to 2022). "In murine models of genetic obesity, a decrease in BAT activation has been reported, probably as a consequence of an association with the reduction of UCP1." (PMID 36142750, 2022).
glucose metabolic disorders (2 papers, 2019 to 2022). "The failure of the α-lipoic acid treatment to impact on insulin resistance, hyperglycemia and hyperinsulinemia indicates that factors other than oxidative stress and UCP-1 downregulation contribute to the glucose metabolic disorders in ZDF rats." (PMID 31888243, 2019).
Hepatic fibrosis (2 papers, 2024). The presence of excessive fibrous connective tissue in the liver. "Progression of liver fibrosis either in MCD-fed UCP1flox/flox-NCR1cre mice or in mice transfused with UCP1−/− NK cells confirmed that a key role of cell-intrinsic deficiency of UCP1 on NK cell bioactivity." (PMID 39033153, 2024). "Moreover, UCP1-deficient NK cells were responsible for the aggravation of liver fibrosis, as confirmed in MCD-fed UCP1flox/flox-NCR1cre mice." (PMID 39033153, 2024). "Therefore, the −3826 A/G polymorphism of UCP1 could affect the biological function of NK cells and the severity of liver fibrosis under high-lipid condition." (PMID 39033153, 2024). "These experiments confirmed that compromised activity of UCP1−/− NK cells under high-lipid microenvironment facilitates hepatitis progression to liver fibrosis." (PMID 39033153, 2024). "Acerbation of liver fibrosis was also seen in wild-type mice when their endogenous NK cells were replaced with UCP1−/− NK cells." (PMID 39033153, 2024). "Although no variated number and function of NK cell were seen in physiologic UCP1−/− mice, compromised NK cell bioactivity was involved in the acerbation of NASH and liver fibrosis in MCD-fed UCP1−/− mice." (PMID 39033153, 2024). "In summary, compromised NK cell activity with decreased UCP1 was involved in the progression of NAFLD, particularly in liver fibrosis." (PMID 39033153, 2024). "Although no obvious changes were observed in the NK cells of physiologic UCP1−/− mice (8–10 weeks old), impaired NK cell bioactivity was shown in methionine–choline-diet (MCD)-fed UCP1−/− mice and involved in the acerbation of nonalcoholic steatohepatitis (NASH) progress to liver fibrosis." (PMID 39033153, 2024).
Hepatitis (2 papers, 2023 to 2024). Inflammation of the liver. "In addition, circulating succinate levels are utilised and cleared by uncoupling protein 1 (UCP1) expressed in brown and beige adipose, and genetic disruption of UCP1 leads to SUCNR1 mediated liver inflammation." (PMID 37484963, 2023).
injury (2 papers, 2016 to 2021). Damage inflicted on the body as the direct or indirect result of an external force, with or without disruption of structural continuity. "Accumulated evidence pointed to significant lipid accumulation and abnormal expression of UCP1 in AKI, as well as strong correlation with the severity of kidney injury." (PMID 33754018, 2021).
kidney cancer (2 papers, 2019 to 2022). Primary or metastatic malignant neoplasm involving the kidney. "In addition, PLCL1 could repress the progression of kidney cancer through UCP1-mediated lipid browning." (PMID 36189312, 2022). "In addition, a recent study has found that phospholipase C-like 1/uncoupling protein 1 mediating lipid browning could promote kidney cancer cell “slimming” and consume abnormal lipid accumulation, which represses the progression of ccRCC." (PMID 31727869, 2019).
leukemia (2 papers, 2015 to 2024). A malignant (clonal) hematologic disorder, involving hematopoietic stem cells and characterized by the presence of primitive or atypical myeloid or lymphoid cells in the bone marrow and the blood. "Knowing the crucial role of BAT in mediating the anti‐leukemia effect of cold exposure, we next deleted the Ucp1 gene in mice." (PMID 39049685, 2024). "Surgical removal of thermogenic brown adipose tissue (BAT) or genetic deletion of uncoupling protein 1 (UCP1) largely abolishes the TATA‐mediated anti‐leukemia effects." (PMID 39049685, 2024).